IL6 (interleukin 6)
Diseases named in the same sentence as IL6 in open-access papers (continued):
Sharing a sentence is not in itself a finding about the gene and the disease.
HIV-1 infection (62 papers, 2007 to 2025). The type species of lentivirus and the etiologic agent of acquired immunodeficiency syndrome (AIDS). "Immune activation and inflammation are associated with high plasma levels of IL-6 and sIL-6R, not only during untreated HIV-1 infection, but during other chronic illness such as multiple sclerosis, B-cell lymphomas, and Type 2 Diabetes." (PMID 37812611, 2023). "Other recent work also suggests that HIV-1 infection in primary human microglia cells causes the release of IL-6, IL-8, TNF-α, CCL2, and regulated-upon-activation, normal T cell-expressed and -secreted (RANTES) proteins." (PMID 34440127, 2021). "High serum levels of IL-6 during HIV-1 infection have been previously associated with increased levels of activated memory B cells." (PMID 25213015, 2014). "During periods of inflammation caused by HIV-1 infection, co-pathogens, or opportunistic infections, levels of circulating cytokines such as IL-6 and TNFα increase and stimulate HIV-1 replication in monocytic cells." (PMID 20030845, 2009). "One might therefore speculate that IL-6 is more likely than sCD14 to indicate pathogenic processes in the innate immune system during chronic untreated HIV-1 infection." (PMID 21526194, 2011). "Furthermore, HIV-1 infection is associated with increased IL6 production." (PMID 35008292, 2021). "HIV-1 infection has long been associated with increased levels of IL-6, and IL-6 can be produced by monocytes in response to both LPS and the HIV-1 accessory protein Vpr, suggesting that both viral and bacterial antigens could contribute to the increased levels of this inflammatory cytokine." (PMID 21526194, 2011). "STAT3 plays a central role in cytokine signaling pathways (particularly IL-6 and IL-10), and type I IFNs, which are dysregulated in HIV-1 infection." (PMID 41009690, 2025). "HIV-1 infection also stimulates the release of IL-6 by endothelial cells, further increasing BBB permeability by disrupting endothelial junctions." (PMID 40420159, 2025). "Although IL-6 has been previously reported to exert protective effects against HIV-1 infection, its downregulation in this context was unexpectedly associated with reduced viral replication." (PMID 41009690, 2025). "Elevated proinflammatory cytokines, such as TNF-α, IL-6, and IL-1β, appeared in the plasma and lymph nodes from the early stage of HIV-1 infection." (PMID 38138916, 2023). "We are not aware of any published literature that examined the correlation among serum levels of IL-6, sIL6R and sgp130 during HIV-1 infection, but there were some reports when looking at other diseases." (PMID 37812611, 2023). "Interleukin 6 and its receptors play an important role in pathogenesis of diseases including HIV-1 infection." (PMID 37812611, 2023). "Increased serum levels of sIL-6R and IL-6 have been observed during the chronic stage of untreated HIV-1-infection, most likely due to residual ongoing production of virus or viral particles." (PMID 37812611, 2023). "Individuals in the early phase of their HIV-1 infection show elevated plasma IL-6 and sIL-6R levels which suggests that HIV-1 plays a central role in inducing and increasing production of IL-6 and sIL-6R in vivo." (PMID 37812611, 2023). "IL-6 and its related receptors in interaction with other cytokines play an important role in the pathogenesis and progression of HIV-1 infection." (PMID 37812611, 2023). "Under the condition of glycolysis inhibition, we observed that the expression of M1 markers TNF-α, IL-1β, and IL-6 was also reversed, indicating that blocking glycolysis inhibits M1 polarization of macrophages driven by HIV-1 infection." (PMID 37798121, 2023). "At the protein level, we observed these M1 inflammatory factors (TNF-α, IL-1β, and IL-6) sustained the release to the supernatant during HIV-1 infection." (PMID 37798121, 2023).
HIV-1 infection (continued). "The expression of IL-8 and IL-6 in HIV-1 infection is induced by HIV glycoprotein 120 (gp120), trans-activator (tat) and viral protein R (vpr) through the nuclear factor-kappa B (NF-kB) pathway." (PMID 36432041, 2022). "Nonetheless, C5a increases TNF-α and IL-6 release, thereby promoting HIV-1 infection, whilst inhibition of its receptor C5aR reverses this action." (PMID 34502066, 2021). "Surprisingly, the IFNβ-specific ISGs that correlated with IL6 were downregulated during chronic HIV-1 infection in the gut." (PMID 33064743, 2020). "In macrophages, Vpr-induced TET2 depletion prevents efficient resolution of IL-6 induction during HIV-1 infection, which enhances HIV-1 infection in macrophages." (PMID 31431548, 2019). "The Vpr-TET2 axis enhances HIV-1 replication in MDMs by reducing IFITM3 expression and by sustaining IL-6 induction after HIV-1 infection." (PMID 31431548, 2019). "We have recently discovered that Vpr targets the DNA demethylase TET2 for degradation, which leads to sustained IL-6 expression and elevated second-round HIV-1 infection." (PMID 31431548, 2019). "Another study showed that HIV-1 infection in primary human microglia induced the secretion of IL-6, IL-8, TNF-α, C-C Motif Chemokine Ligand 2 (CCL2), and Regulated upon Activation, Normal T cell Expressed and Secreted protein (RANTES)." (PMID 31614895, 2019). "Other inflammatory markers reported during HIV-1 infection are IL-6 and the acute-phase reactant CRP; both have been previously correlated with mortality in HIV-1 individuals." (PMID 29963050, 2018). "Consistent with their ability to activate STAT3, IL-6 and IL-10 also induced miR-29 and suppressed HIV-1 infection in HLACs." (PMID 26108174, 2015). "In response to opsonised IE, HIV-1 infection significantly reduced IL-6 mRNA at 2 hours (p = 0.002), 1 hour (p = 0.026; data not shown) and 4 hours (p = 0.04; data not shown)." (PMID 22363802, 2012). "Milk from two of these subjects contained high levels of multiple pro-inflammatory cytokines including TNFα, IL-1β, IL-6, IL-8, MIP-1α, MIP-1β, MCP-1 and IP-10, and enhanced cell-associated HIV-1 infection at dilutions as high as 1∶500." (PMID 22952771, 2012). "In both case, the result is a high level of pro-inflammatory cytokines, such as tumor necrosis factor alpha, interleukin 6 and interleukin 1 beta, right from the early stages of HIV-1 infection." (PMID 21362195, 2011). "Our results demonstrate that HFA can be triggered to IL-6 expression by HIV-1 binding but that HIV-1 infection by VSV-G/pseudotyped, gp120-negative virus capable of expressing all other viral genes cannot trigger this gene expression." (PMID 17498309, 2007). "Moreover, foetal human microglia can develop senescent markers such as SA-β-Gal activity, p21 expression, and production of IL-6 and IL-8 as a result of HIV-1 infection." (PMID 39828750, 2025). "Conversely, IL-6-mediated enhancement of HIV-1 infection was unaffected by GJB2 depletion." (PMID 40980890, 2025). "HIV-1 infection is accompanied by dysregulation of cytokine production in vivo and in vitro, with downregulation of interleukin (IL)-2 and interferons and upregulation of proinflammatory cytokines IL-1, IL-4, IL-6, IL-10, and TNFα." (PMID 38280430, 2024). "HIV-1 infection typically results in the production of proinflammatory cytokines (IL-6) and IFNα." (PMID 38528047, 2024). "In addition, asymptomatic children and children presenting subacute encephalopathy with coexisting HIV-1 infection had confirmed increased levels of FLCs and interleukin-6 (IL-6) or macrophage colony-stimulating factor (M-CSF)." (PMID 37298479, 2023). "Interestingly, chronic HIV-1 infection, even in the setting of long-term suppressive antiretroviral therapy, leads to increases in similar inflammation markers such as IL-6 and C-reactive protein." (PMID 36454631, 2023). "The ratio of IL6R/IL6 was higher in our study which may be due to differences in gender and chronicity of HIV-1 infection." (PMID 37812611, 2023).
HIV-1 infection (continued). "Thus, EVs circulating in the plasma of HIV-1-infected individuals stimulate the release of Gal-1 along with IL-6 from macrophages, suggesting a regulatory role for this glycan-binding protein during HIV-1 infection and persistent immune activation." (PMID 35943163, 2022). "Furthermore, plasma inflammatory cytokine levels of sCD14, sCD163, interleukin 6, and lipopolysaccharide binding protein were significantly higher in SC with p<0.05 before HIV-1 infection compared to NC." (PMID 34879869, 2021). "Interestingly, IL-1β and IL-6 enhance HIV-1 infection in monocytes and resting CD4+ T cells in vitro." (PMID 25785697, 2015). "In the current study, to investigate the impact of HIV-1 infection on B cell aging, we have compared the frequency, surface markers and intracellular IL-6 expression in response to activation of multiple B cell subsets in the blood of healthy and HIV-1 infected individuals." (PMID 25213015, 2014). "In response to opsonised IE, HIV-1 infection significantly reduced IL-6 release (1,116 pg/mL (IQR: 352–3,387) compared to 1,552 pg/mL (IQR: 889–6,331); p = 0.0078) and IL-1β release (16 pg/mL (IQR: 7–21) compared to 33 pg/mL (IQR: 27–65); p = 0.0078) from mock-infected IFNγ primed MDM." (PMID 22363802, 2012). "As expected, HIV-1 infection induced expression of IL-1β, IL-6, TNF-α and CXCL8." (PMID 20877724, 2010). "Similar to what is observed during aging, HIV-1 infection can generate an inflammatory environment by causing the release of viral proteins (such as Tat and gp120) and cellular products (such as proinflammatory cytokines, e.g., TNF-α, IL-8, IL-6, and IL-1β) from cells." (PMID 31614895, 2019). "Although myeloid cells are more resistant to HIV-1 infection than CD4+ T cells, some cytokines, including interleukin (IL)-4 and IL-6, promote myeloid cell infection." (PMID 40980890, 2025). "Data from other studies found that interleukin-6 [IL-6], C-reactive protein [hsCRP], soluble CD14 [sCD14], and D-dimer correlated with the overall mortality due to HIV-1 infection." (PMID 39205179, 2024). "The median serum levels of IL-6 and sIL-6R was higher in acute SARS-CoV-2 patients than in the men in our study who were living with chronic HIV-1 infection (34.9 pg/mL vs 1.68 pg/mL for IL-6 and 40.25 ng/mL vs 34.8 ng/mL for sIL-6R respectively)." (PMID 37812611, 2023). "The HIV-1 infection of TZM-bl cells did have an effect; we observed decreased levels of IL-2 and CCL2 and increased levels of IL-6 and IL-8." (PMID 36432041, 2022). "In the context of HIV-1 infection, TET2 protein degradation via Vpr protein similarly sustains IL-6 production, which enhances virus replication." (PMID 35115654, 2022). "In our current study, significantly high levels of pro-inflammatory cytokine sCD14, sCD163, IL-6, and LBP were detected in SC prior to HIV-1 infection compared to NC (p<0.05)." (PMID 34879869, 2021). "Despite the immunodeficiency during HIV-1 infection, HIV-1 exploits our cellular defence arsenal by escaping cell-mediated lysis, yet HIV-1 infectivity is enhanced via C5a release of TNF-α and IL-6." (PMID 34502066, 2021). "Here we assessed plasma levels of soluble CD14 (sCD14), C-reactive protein (CRP), IL-6, and intestinal fatty acid binding protein (IFABP) at the pre-infection time point and over the course of the first 45 days of acute HIV-1 infection." (PMID 31937782, 2020). "We further analyzed spreading HIV-1 infection of Vpr+ and Vpr− HIV-1 in MDMs for 6 days with depletion of TET2 or IFITM3 treated with IL-6 neutralizing antibody." (PMID 31431548, 2019). "The Vpr-TET2 axis enhances HIV-1 infection in MDMs by reducing IFITM3 expression via a TET2 dioxygenase-dependent mechanism and by sustaining IL-6 induction via TET2 dioxygenase-independent mechanisms." (PMID 31431548, 2019). "Cytokines affected by HHODC in this study, IL-2, IL-6, TNF-α, and IFN-γ, are documented as being among the many biomarkers affected by HIV-1 infection due to immune dysfunction." (PMID 29027985, 2017).
HIV-1 infection (continued). "A number of pro-inflammatory cytokines (TNF-α, IL-1β, IL-6, IFN-γ) and oxidative stress markers (such as nitric oxide) are known to be elevated during brain HIV-1 infection." (PMID 24884548, 2014). "In contrast, GJB2 expression was unaffected by both the presence and absence of cytokine IL-6, which was reported to promote HIV-1 infection in primary macrophages." (PMID 40980890, 2025). "Finally, we determined that IL-6—a cytokine regulated by DDX3X and ZC3HAV1—also changes its expression levels during the different stages of HIV-1 infection in microglia." (PMID 40429887, 2025). "Additionally, we determined that IL-6, a cytokine regulated by DDX3X and ZC3HAV1, exhibits changes in protein expression levels during both active and persistent HIV-1 infection." (PMID 40429887, 2025). "Our results showed that both IL-4 and IL-6 promoted HIV-1 infection without disrupting the GJB2 loci." (PMID 40980890, 2025). "In human cells, increased expression of proinflammatory cytokines such as tumor necrosis factor alpha (TNF-α), interleukin 6 (IL-6), and interleukin-12, which contribute to HIV-induced immune activation, can be triggered by Toll-like receptor (TLR) 8 sensing of HIV-1 infection." (PMID 39459950, 2024). "High levels of pro-inflammatory cytokines, such as tumour necrosis factor alpha (TNFα), interleukin 6 (IL-6) and interleukin 1 beta (IL-1β) in both plasma and lymph nodes, are observed from the early stages of HIV-1 infection." (PMID 34112126, 2021). "Recent findings suggest that HIV-1 infection can produce an inflammatory environment due to the induction of viral proteins (such as Tat and gp120) and proinflammatory cytokines (e.g., TNF-α, IL-8, IL-6, and IL-1β)." (PMID 34440127, 2021). "The expression level of IL-1β and IL-6 remained below the threshold of detection in MF supernatants even after HIV-1 infection, and the level of TNF-α mRNA was not modified upon infection." (PMID 32365752, 2020). "Many studies have previously reported a correlation between the observed increase in the production of pro-inflammatory cytokines IL-1β, IL-6, IL-18 and TNF-α; and IFN inducible chemokines CXCL9, CXCL10 and CXCL11 during the course of HIV-1 infection and the up regulation of HIV-1 replication." (PMID 29373606, 2018). "Additionally, unlike IL-4, the IL-6-mediated enhancement of HIV-1 infection in macrophages was unrelated to GJB2." (PMID 40980890, 2025). "Therefore, IL-4 but not IL-6 downregulated GJB2 to promote HIV-1 infection in macrophages." (PMID 40980890, 2025). "Our findings showed that GJB2 silencing impaired IL-4- but not IL-6-mediated enhancement of HIV-1 infection, suggesting that IL-4-mediated downregulation of GJB2 expression enhanced HIV-1 infection." (PMID 40980890, 2025). "Concordantly, we observed a rapid elevation in the plasma levels of several pro-inflammatory cytokines such as IFN-γ, IL-18, and IP-10 but not of IL-6 and TNFα that remained below the LOD in most of mice plasma upon HIV-1 infection." (PMID 36800238, 2023). "Compared to mock-infected MDM, HIV-1 infection significantly inhibited phagocytosis of opsonised IE without altering MDM viability, and decreased secretion of IL-6 and IL-1β." (PMID 22363802, 2012). "Production of IL-12, IL-6, CCL-2, CXCL-10 and CXCL-12, that were also detected at day 14, was not significantly affected by either R5 or X4 HIV-1 infection (data not show)." (PMID 21767373, 2011). "Not surprisingly, HIV-1 infection alters the PKC phosphorylation pathway to stimulate TNF-α production by monocytes as well as other cytokines and growth factors such as IL-6, IL-10, and MCP-1." (PMID 20604950, 2010).
Encephalopathy (61 papers, 2008 to 2025). Encephalopathy is a term that means brain disease, damage, or malfunction. "Elevated levels of interleukins IL-6 and IL-10 have been implicated in influenza-associated encephalopathy and correlate with disease severity." (PMID 40416295, 2025). "APACHE II, SOFA, age, tau protein, IL-6, and albumin were associated with sepsis-related encephalopathy and were supported by medium- to high-quality evidence." (PMID 38835794, 2024). "For example, encephalopathy has been associated with increased serum IL-6 levels, a predictor of poor prognosis." (PMID 37109156, 2023). "High serum levels of IL-6 in patients with influenza virus-associated encephalopathy were associated with poor clinical prognosis including neurological sequelae and death." (PMID 32850927, 2020). "Serum concentrations of IL6 were increased in neonates with asphyxiaafter birth and this was associated with the severity of encephalopathy and pooroutcomes." (PMID 31435616, 2019). "In particular, increased IL-6 and TNFα is linked to a poor prognosis in infants suffering encephalopathy, these factors known to stimulate extrinsic pathways of cell death." (PMID 23454862, 2013). "Thus, it is possible that IL-6 may play a central role in a range of infection-associated encephalopathies." (PMID 35058867, 2021). "Studies have demonstrated that higher IL-6 concentrations correlate with worse clinical outcomes in septic patients, including increased severity of encephalopathy and higher mortality rates." (PMID 40635709, 2025). "Multivariate logistic regression identified several risk factors for encephalopathy in septic patients, including age, APACHE II score, LDH, IL-6, oxygenation index, BE, and BE(ecf)." (PMID 40635709, 2025). "We found that several mediators previously associated with encephalopathy in clinical samples were upregulated in the lung, including CCL2, and IL-6." (PMID 39474424, 2024). "Fourth, a patient with norovirus-associated encephalopathy showed elevated concentrations of cerebrospinal fluid interleukin-6, interleukin-10, interferon-γ, and tumor necrosis factor-α suggesting that her encephalopathy was related to hypercytokinemia." (PMID 37477790, 2023). "Although microglia have protective activity, hyperactivated microglia release high levels of inflammatory cytokines such as IL-6, IL-1β, and TNF-α, leading to neuronal death and chronic inflammation, which is the degenerative main cause of encephalopathy." (PMID 36176437, 2022). "Future studies should include a cytokine profile to disentangle the pathogenesis of this encephalopathy and other inflammatory markers, such as fibrinogen and IL-6, as CSF cytokine alterations have been highlighted in COVID-19 encephalopathy patients." (PMID 34709472, 2021). "IL-6 and TNFα are the signature cytokines of lung inflammation and have been associated with severe RSV diseases such as severe bronchiolitis and encephalopathy." (PMID 34929018, 2021). "Previous studies reported increased serum and cerebrospinal fluid concentrations of IL-1β, IL-6, IL-10, and TNF-α, as well as increased transcription of their coding genes in patients with influenza-associated encephalopathy and FS." (PMID 34300253, 2021). "CSF biomarkers FasL and IL-6 predicted severity of encephalopathy and long-term outcomes in post-asphyxiated infants better than a standard biomarker." (PMID 30089504, 2018). "RSV-induced encephalopathy is accompanied by neuronal cell damage and frequently altered expression levels of pro-inflammatory cytokines, such as IL-6, IL-8 and TNF-α." (PMID 29427996, 2018). "Marked IL-6 responses have been found in cases of severe HPAIV infection in humans and mice and in cases of influenza virus infection-associated encephalopathy." (PMID 23874602, 2013). "Considering both her serious clinical condition and elevated serum levels of interleukin-6, we speculated that her condition was similar to cytokine-storm-induced encephalopathy." (PMID 34188964, 2021).